MIF (macrophage migration inhibitory factor)
Diseases named in the same sentence as MIF in open-access papers (continued):
Sharing a sentence is not in itself a finding about the gene and the disease.
cancer (continued). "sCD74 can interact with macrophage migration inhibitory factor (MIF), leading to activation of signaling pathways that promote cancer cell survival and proliferation." (PMID 39910579, 2025). "Studies have shown that the importance of MIF and IFN-II in cancer has been confirmed in many clinically relevant cancer models and is closely related to cancer development." (PMID 41235252, 2025). "The results demonstrated that cancer cells interact with stromal cells via the PTN-NCL and MIF-(CD74+CXCR4) signaling pathways." (PMID 40642071, 2025). "The interaction of MIF with its receptors (CD44, CD74, CXCR4) are known drivers in late stage MM and other cancers and are involved in a variety of mechanisms, including homing to BM, pro-tumoral M0 macrophage differentiation and resistance to therapy." (PMID 41056512, 2025). "According to a study, MIF was found to regulate secreted phosphoprotein 1 (SPP1) and increase TAM migration to HCC cells, and resulted in increased cancer metastasis and invasion." (PMID 41159021, 2025). "MIF antagonists, such as ISO-1 and 4-IPP, have been explored as potential therapeutic agents for cancer." (PMID 41159021, 2025). "To support their possible roles in crucial oncogenic mechanisms, we assessed the mutation frequency, copy number amplification, and copy number–expression correlation of STC2, MIF, CD74, CXCR4, GDF15, and TGFBR2 across several cancer types." (PMID 41502509, 2025). "In high ICDRS tumors, cancer cells exhibited more complex intercellular communication networks, establishing extensive signal exchanges with the microenvironment via MDK and MIF signaling pathways." (PMID 41200185, 2025). "Cell communication analysis indicated strong interactions between CD2AP+ cancer cells and monocytes, predominantly mediated by the APP-CD74, MIF-CD74_CD44, and SCGB3A2-MARCO pathways." (PMID 41425578, 2025). "MIF and DDT have been studied extensively in a variety of preclinical and clinical cancer models, including those of hematologic, musculoskeletal, gastrointestinal, and gynecologic origin." (PMID 39028303, 2024). "Across all donors, MIF and SPP1 signalling was prominent in cancer cells while SPP1 signalling was also active in M2 macrophages." (PMID 39149248, 2024). "Among these, two of the majors signaling molecules, MIF and SPP1, were mainly secreted by a subpopulation of cancer stem cells." (PMID 38191424, 2024). "Both MSCs and A431 cells secreted MIF, SERPIN1, IL-8, and CXCL1/GRO⍺, while CCL2 and IL-6 were only found in MSC cultures, and CCL5 and GM-CSF were only detected in cancer cell supernatants." (PMID 38674102, 2024). "COPA affects cancer therapeutic response through the remodeling of immune microenvironment in a variety of cancers, and activation of CD74-APP/COPA/MIF on the surface of B cells facilitates the suppressive immunomodulatory effects of M2 macrophages and Tregs." (PMID 39422621, 2024). "MIF and DDT promote cell regeneration and proliferation in cancer by activating the ERK1/2, PI3K-Akt, NFκB, and AMPK pathways, which subsequently activate downstream NF-κB/P-TEFb complexes and drive c-Myb transcription." (PMID 38732068, 2024). "While a comprehensive discussion of MIF and CD74 in cancer is outside the scope of this work, the interested reader is referred to several excellent reviews on this topic." (PMID 38730725, 2024). "Collagens, MIF, MDK, APP, and laminin were the most highly expressed, and the top ligand-receptor interactions were CAF derived THBS2/THBS3 with cancer cell CD47, and CAF-derived MDK with cancer cell NCL/SDC2/SDC4." (PMID 38525245, 2024). "Our findings highlight the importance of MIF in CAF signalling and its potential as a prognostic factor and therapeutic target in cancer." (PMID 38520216, 2024). "Macrophage migration inhibitory factor (MIF) is an integral cytokine for the modulation of both innate and adaptive immunity and is involved in the pathogenesis of various cancers." (PMID 38916819, 2024).
cancer (continued). "In the 4T1 BC model, reducing the levels of the immunoregulatory cytokine Macrophage Migration Inhibitory Factor (MIF), which is frequently overexpressed in various cancers, significantly enhances ICD in vitro, particularly under serum-free conditions." (PMID 38994937, 2024). "MIF and SPP1 play critical roles in various diseases, including cancer, and present promising therapeutic targets." (PMID 38191424, 2024). "Signaling molecules such as MIF and SPP1 are predominantly delivered by the C2-E.T cluster and represent main the pro-cancer signals between cells in the early stages of tumorigenesis." (PMID 38191424, 2024). "Discovered as inflammatory cytokines, MIF and DDT exhibit widespread expression and have emerged as critical mediators in the response to infection, inflammation, and more recently, in cancer." (PMID 38732068, 2024). "Secreted factors such as MIF, IL‐6, CD40L, FST, SDF‐1α and IL‐8 were expressed at higher levels in conditioned medium from PC3 cancer cells." (PMID 36608258, 2023). "A number of cell membrane proteins such as N-myristoyltransferase 1 (NMT 1), CD71, Ep-CAM and MIF are seen to be extracted by MGL differentially from C1GalT1-expressing and knockdown cancer cells in this study." (PMID 37612278, 2023). "Recently, 4-IPP has been shown to block MIF/receptor interactions and to be more effective than ISO-1 in preventing migration, and invasion in human cancer cell lines through MAPK and NF-κB signals." (PMID 37674165, 2023). "For instance, in renal cancer cell lines, the individual, as well as the combined knockdown of MIF and DDT, affected many cancer features, such as the invasion, migration, and proliferation rates." (PMID 36672343, 2023). "The macrophage migration inhibitory factor (MIF) family of cytokines, comprising MIF and DDT (also known as MIF2), are overexpressed in almost all cancer types, and their high expressions are related to a worse prognosis for the patients." (PMID 36672343, 2023). "It has been found that MIF works in conjunction with high doses of PRG to inhibit endometrial cancer cell growth, and has known anti-cancer properties." (PMID 36984647, 2023). "MIF can activate the PI3K and MAPK pathways and modulate apoptosis, differentiation, proliferation, cell survival, and cancer progression." (PMID 38235128, 2023). "Our data further showed that CD36+ CAF-derived MIF promotes immunosuppressive TME and cancer stemness by enhancing MDSC expansion and suppressing T-cell-mediated antitumor immunity." (PMID 36878933, 2023). "It has now become clear that the binding of MIF and DDT to their receptors and/or intracellular targets has a strong effect on cancer promotion." (PMID 36672343, 2023). "Therefore, dual inhibitors of MIF and D-DT may be needed for the treatment of cancer." (PMID 35091838, 2022). "MIF is an upstream modulator of IL-6 and the IL-6/JAK/STAT pathway and has a vital impact on the growth and development of many human cancers." (PMID 36042480, 2022). "Conversely, knockdown of MIF in TA-MSCs reduced FTO expression and attenuated the cancer-promoting effect." (PMID 35794625, 2022). "It was demonstrated that elevated levels of MIF can enhance the growth inhibition and induction of apoptosis triggered by high doses of PRG in nPR(+/-) cancer cells." (PMID 36246881, 2022). "MIF can bind to its receptor CD74 in the TME, which is present on TAMs, DCs, Treg cells, and MDSCs, facilitating immunological escape and cancer growth." (PMID 35967424, 2022). "MIF-based therapeutics, ranging from small molecule inhibitors to anti-MIF antibodies, have for instance showed promise in SLE, RA and cancer." (PMID 35465102, 2022). "Cytokines such as MIF, IL-6, and TGF-β used as adjuvants in cancer treatment has been extensively investigated in many clinical studies." (PMID 36313280, 2022).
cancer (continued). "explored Mycobacterium smegmatis delivering a fusion protein comprising human macrophage migration inhibitory factor (MIF) and IL-7 as cancer vaccines to struggle against tumors." (PMID 36389666, 2022). "The top outgoing signaling from epithelial cancer cells to CAFs (communication probability > 0.10) showed interactions between MIF (cancer cells) and CD74 + CD44 (CAFs) or MDK (cancer cells) and NCL/SDC2/LRP1 (CAFs)." (PMID 36352420, 2022). "Accurate and convenient detection of MIF and MIF2 will facilitate research on their roles in cancer and other diseases." (PMID 34724273, 2022). "Macrophage migration inhibitory factor (MIF) is involved in protein‐protein interactions that play key roles in inflammation and cancer." (PMID 34018657, 2021). "These pro-metastatic EVs of PDA cancer cell lines and PDA patients’ sera upregulate macrophage migration inhibitory factor (MIF) as early as the formation of PanINs." (PMID 34207163, 2021). "In conclusion, we describe the first MIF‐directed PROTAC (MD13) as a research tool, which also demonstrates the potential of PROTACs in cancer therapy." (PMID 34018657, 2021). "This assumption was confirmed when the expression of MIF and GPC-1 proteins in EVs was detected in cancer patients, allowing them to analyze the prognosis of cancer." (PMID 34805181, 2021). "MIF promotes monocyte and neutrophil recruitment through CXCR2, while enhancing T-cell, B-cell, and progenitor cell recruitment, as well as cancer cell metastasis through CXCR4." (PMID 35087852, 2021). "It has been reported that MIF is abnormally overexpressed in human HNSC, which promotes the cancer progression." (PMID 35036405, 2021). "The cytokine macrophage migration inhibitory factor (MIF) is highly expressed in various tumors, including GC, and stimulates proliferation and inhibits apoptosis in cancer cells." (PMID 34830815, 2021). "Emerging evidence suggests that inflammatory cytokines including MIF, TNF-α, interferon gamma, and transforming growth factor beta are increased in the setting of cancer." (PMID 33776775, 2021). "Targeting MIF is of interest due to our previous work where we observed that MIF derived from GBM cells, specifically therapeutically resistant cancer stem cells (CSCs), was necessary for MDSC survival and function." (PMID 32625208, 2020). "In another study, MIF was also demonstrated to restrict nuclear receptor subfamily 3 group C member 2 (NR3C2), which negatively regulates EMT-promoting factors in cancer cells." (PMID 32756339, 2020). "Macrophage migration inhibitory factor (MIF) is derived from GBM cells, precisely medicinally resistant cancer stem cells, and it is obligatory for MDSC survival and function." (PMID 33204365, 2020). "MIF has previously been described to be transcriptionally regulated by HIF-1α in cells of the trachea, lung and in cancer cells." (PMID 32885302, 2020). "We analyzed the cancer genome atlas (TCGA) GBMLGG database for survival and MIF expression and CD74 expression and the combination." (PMID 32625208, 2020). "The growing body of evidence suggesting a major role for the MIF and DDT in cancer development has attracted interest in the study of its involvement in the pathogenesis and progression of NB." (PMID 32155795, 2020). "Bioinformatic analyses, performed to assess the role of 41 cytokines after RT exposure and their network interactions, suggested TGF-β, MIF, CCL2, CXCL5, CXCL8 and CXCL12 as master regulators of cancer immune escape in RMS tumors." (PMID 32854690, 2020). "Our results strongly suggest that the inhibition of autophagy should be combined with pro-inflammatory cytokine modulation, and particularly MIF inhibitors, for a better outcome during TNBC cancer therapy." (PMID 31963754, 2020).
cancer (continued). "In a similar manner an anti-MIF mAb (BAX69) has been tested in Phase II studies (NCT02540356 and NCT02448810) in cancer patients." (PMID 31635049, 2019). "The ROC analysis comparing patients with ICC to Ctrl HPV− revealed that five tested cancer biomarkers: TNFα, CYFRA 21-1, macrophage migration inhibitory factor (MIF), prolactin and SCF had AUC greater than 0.8." (PMID 31089160, 2019). "Different drugs targeting MIF and its main receptor CD74 are in clinical development in many diseases, including cancer." (PMID 29875777, 2018). "MIF-inhibition by ISO-1 has been proven to inhibit viability and function of several human cancer cell lines such as, A549, DU145, LN229, LN-18 and HS683." (PMID 29707160, 2018). "Several studies reported a role for macrophage migration inhibitory factor (MIF) in promoting MDSC and macrophage accumulation and immunosuppressive activity in several cancers." (PMID 29949929, 2018). "Because CD74 and CD44 are both involved in MIF-mediated signalling, CD74 is considered a potential therapeutic target in cancer." (PMID 29190904, 2017). "Our results support the concept that CSCs, through the expression of MIF and CD74, become protected by energy-default processes which force cancer cells with defective mitochondria to generate energy through an AMPK-regulated glycolysis in the cytoplasm." (PMID 28114961, 2017). "For mir-451, several genes have been validated as its targets in cancer, including c-myc, ras-related protein 14 (RAB14), MDR-1 and Macrophage migration inhibitory factor (MIF)." (PMID 28704499, 2017). "In contrast, other studies showed that MIF can activate the AMPK pathway, leading in some cancers to a decrease in cell proliferation, cell viability and in their metastatic potential." (PMID 26883190, 2016). "Macrophage migration inhibitory factor (MIF) is a pleiotropic cytokine with proinflammatory and prosurvival effects involved a variety of human disease states, including cancer." (PMID 26741693, 2016). "The effect of MIF and CD74 on carcinogenesis seems to change with the cell type as well as the stage of the cancer." (PMID 26883190, 2016). "Chemokine functions of MIF are expected to play an important role in altering the TME as they contribute to the infiltration of leukocytes into tumors, thereby promoting cancer related inflammation." (PMID 27636991, 2016). "Macrophage migration inhibitory factor (MIF) hits 15 alkaloids (C1–2, C11–16, C19–25) was the most promising target related to cancer." (PMID 26691584, 2015). "Macrophage migration inhibitory factor (MIF), a proinflammatory and immunoregulatory chemokine, plays important roles in cancer-related biological processes." (PMID 25015194, 2014). "It is also noteworthy that, compared to ASCs-CM, hUCESCs-CM contain lower levels of factors known to participate in cancer progression, such as EGFR, FGF 4 and 9, ICAM3, IL6, IL6R, MCP3 (CCL7), MIF, sgp130 and VEGFD." (PMID 25296979, 2014). "These considerations led us to an immunohistochemical assessment of expression of MIF and CD74 in serial sections of human breast cancer tumor specimens, mapping their profiles in cancer and stromal cells." (PMID 24939415, 2014). "In this respect, our study is the first to report the semi-quantitative immunohistochemical evaluation of both expression of MIF and CD74 in serial sections of biopsy specimens, as well as their distribution between cancer cells and the peritumoral stroma." (PMID 24939415, 2014). "Based on these findings we investigated the functional relationship between MIF and HIF-1 in human cancer cells." (PMID 18493321, 2008). "Furthermore, the inhibition of the CXCR7 receptor blocked MIF-induced proliferation, highlighting CXCR7’s role in cancer progression." (PMID 41159021, 2025).
cancer (continued). "Potential mechanisms for CNS recruitment may involve the HIF-1α/MIF pathway, known to mediate MDSC trafficking in cancer, given the elevated cerebrospinal fluid MIF levels observed in AD patients." (PMID 40740772, 2025). "Next to its classical role in MHC II-mediated antigen presentation, CD74 was identified as a high-affinity receptor for macrophage migration inhibitory factor (MIF), a pleiotropic cytokine and major determinant of various acute and chronic inflammatory conditions, cardiovascular diseases and cancer." (PMID 38992165, 2024). "In addition to their known effects in normal cells and systems, MIF and CD74 are increasingly recognized as playing an intricate role in cancer progression." (PMID 38730725, 2024). "The role of MIF in human papillomavirus (HPV)+ and HPV− cancers has been described, but mechanistically, it remains unclear." (PMID 38732068, 2024). "MIF activates MAPK and PI3K pathways involved in signal transduction cascades in many cancers." (PMID 38178143, 2024). "MIF/DDT/CD74 are potential biomarkers and therapeutic targets across a variety of cancers." (PMID 38732068, 2024). "Thus, targeting MIF and DDT holds promise for improving ICI response in these highly lethal cancers." (PMID 38732068, 2024). "Further, both MIF and CD74 are important players in immune homeostasis and cancer." (PMID 38730725, 2024). "Though MIF and DDT have been widely described in inflammation and autoimmunity, interest in these cytokines within oncology has also been relatively recent given their roles in driving cancer hallmarks and their overexpression across a variety of cancers." (PMID 38732068, 2024). "MIF and DDT play pivotal roles in multiple facets of cancer progression and possibly initiation." (PMID 38732068, 2024). "To date, only a limited number of clinical trials have explored MIF as a therapeutic target in cancer patients, and DDT has not been evaluated." (PMID 38732068, 2024). "Several different anti-cancer and GBM treatment approaches based on MIF inhibition have been proposed and include competitive, irreversible and endogenous inhibitors, molecules that destabilize MIF, and monoclonal antibodies blocking MIF or CD74." (PMID 38178143, 2024). "Extensive experimental and computational research has unveiled intricate signaling mechanisms in MIF/DDT/CD74 pathways across diverse cancer types, shedding light on the complexity of canonical and non-canonical signaling processes within the TME." (PMID 38732068, 2024). "Outgoing signaling patterns upregulated in LE-LE signaling, relative to TC-TC signaling, included Collagen, Laminin, Tenascin, FN1, MIF, APP, CD99, Notch, and CSPG4 pathways, reinforcing the role of these pathways in facilitating cancer invasion and metastasis." (PMID 37596273, 2023). "Our study suggests that TREM1, MAPK1, MAPK8, CTSB, MIF, and DPP4 proteins may be targeted by compounds in medicinal plants for their anti-cancer effects." (PMID 37454152, 2023). "Remarkably, MIF-(CD74+CD44) signalling between hepatocytes and T/NK and macrophages, which mediates immunosuppressive effects that have previously been illustrated for promoting cancer progression." (PMID 36860314, 2023). "Considering the involvement of MIF and DDT in multiple hallmarks of cancer, this cytokine family could be considered a promising therapeutic/pharmacological target in cancer treatment." (PMID 36672343, 2023). "MIF can also interact with chemokine receptors such as CXCR2, CXCR4, and CXCR7, which are present in different types of cells (monocytes, neutrophils, DCs, B cells, and cancer cells, among others), thereby promoting their migration." (PMID 36672343, 2023). "In addition, the administration of a small synthetic MIF inhibitor, CPSI-1306, to cancer cells in vitro had a detrimental effect on their proliferation and survival." (PMID 36672343, 2023).